BRCA2 (BRCA2 DNA repair associated)
Diseases named in the same sentence as BRCA2 in open-access papers (continued):
Sharing a sentence is not in itself a finding about the gene and the disease.
cancer (continued). "In BRCA2-mutant cancer cells, G4 binders induced R-loop accumulation followed by double-strand break and micronuclei aggregation." (PMID 37108225, 2023). "In the search for additional synthetic lethal targets, APE2 is over-expressed in many cancers and has emerged as a novel endonuclease that is required for the survival of cancer cells deficient in BRCA1, BRCA2 or TDP1." (PMID 37645072, 2023). "These tumours often show strong geno-phenotypic correlation, with BRCA1 carriers showing increased representation of basal phenotype cancers in women, and BRCA2 carriers showing increased representation of micropapillary-type cancers in men." (PMID 36831687, 2023). "Cancers with BRCA1 and BRCA2 mutations are thought to be highly dependent on Polθ activity for their survival." (PMID 38001070, 2023). "Independently from their role in canonical homologous recombination, BRCA1 and BRCA2 are required for the protection of newly replicated DNA from promiscuous nuclease activities, a function with important implications for both cancer biology and therapy." (PMID 37364916, 2023). "CNV analysis indicated that heterozygous deletion of ARID1A was prevalent in ESCA and KICH; BRCA2 CNV deletion was more common in Pan-cancer than BRCA1 CNV deletion." (PMID 37264024, 2023). "presented BRCA1 and BRCA2 cancer biology and then introduced the relevant disease modelling systems, thus, providing guidance in drug design." (PMID 37476378, 2023). "During follow-up, subsequent cancers were more frequently diagnosed in BRCA patients (19.0% in BRCA1 vs. 21.0% in BRCA2 vs. 5.9% in BRCA-wt, p = 0.002)." (PMID 38067403, 2023). "Recently, it was shown that cancer-causing missense mutations mapped to the HD and OB1 motifs affect the binding with DSS1 allowing mis-localization of BRCA2 to the cytoplasm and defective HR in DNA repair process." (PMID 37168384, 2023). "Cancers with HRR defects (e.g., BRCA1 and BRCA2 mutations) are targets for PARP inhibitors (PARPis) based on the exploitation of “synthetic lethality”." (PMID 37892162, 2023). "IRF9 suppression is also expected to impair the cancer-protective effects of BRCA2 and has been found to promote a powerful immunoinflammatory response associated with lethal neurological disease." (PMID 37626783, 2023). "Our analysis identified 2,793 human genes associated with various diseases, including those associated with cancers (such as BRCA1 and BRCA2) and cardiovascular diseases (such as PDE4D)." (PMID 36950105, 2023). "Inhibition of Pol θ is lethal in HR-deficient cancer cells with BRCA1 and BRCA2 mutations, making Pol θ-mediated MMEJ a promising target for precision cancer therapy." (PMID 36583344, 2023). "The concept of synthetic lethality promotes the development of PARP inhibitors in cancers possessing the defect of homologous recombination repair (HRR), especially those with biallelic loss of BRCA1 and BRCA2." (PMID 36765522, 2023). "Cancer cells harboring mutations in genes involved in homologous recombination (HR)‐mediated DNA repair such as BRCA1 and BRCA2 are exquisitely sensitive to poly(ADP‐ribose) polymerase (PARP) inhibitors." (PMID 37492888, 2023). "A meta-analysis suggests that PGVs in BRCA1, BRCA2, and MMR genes contribute to reduced penetrance to cancer risk in children and adolescents." (PMID 37916805, 2023). "Our study found an overall 4.1% rate of cancer in mutation carriers undergoing risk-reducing surgery, including two with BRCA1 mutation and one with BRCA2 mutation." (PMID 37386498, 2023).
cancer (continued). "In contrast, BRCA2 cancers tended to be luminal or luminal-human epidermal growth factor receptor 2 subtypes." (PMID 36905492, 2023). "Among these features, genomic markers are closely related to mutations and cancer metastasis, with BRCA1, BRCA2, and PIK3CA being previous impact markers." (PMID 36765522, 2023). "The lifetime risk of developing breast, ovarian and other cancers is significantly increased in BRCA1 and BRCA2 mutation carriers." (PMID 37713444, 2023). "For cancer-free AJ women the probability of having a pathogenic mutation in CHEK2 is 1.4%–1.7% and the chance for a mutation in BRCA1 or BRCA2 is less than 2.5%." (PMID 36845387, 2023). "For example, the amplification of the HER2 gene can lead to the rapid growth and spread of cancer cells, and the expression of BRCA1, BRCA2, EGFR, and PIK3CA can also increase the proliferation and migration risk of cancer cells." (PMID 37960513, 2023). "Most notably, racial differences between Black and White samples in the expression of genes pertaining to homology-directed repair, including RAD50, RAD51, MRE11, ERCC1, and BRCA2, were observed in five cancer types." (PMID 37345032, 2023). "In adult patients with cancer, BRCA1 and BRCA2 variants are tissue-restricted biomarkers for PARP inhibitor sensitivity." (PMID 36585449, 2023). "We note that our studies and the experimental systems described herein will be highly valuable for addressing how cancer-associated mutations in the DBD and CTRB affect the functions of BRCA2 in DNA damage repair and DNA replication fork protection." (PMID 36702902, 2023). "The most common genes in which PPGVs were identified pan-cancer were BRCA2 (16.9% of PPGVs), MUTYH (15.0%), ATM (13.4%), CHEK2 (11.7%), and BRCA1 (9.8%)." (PMID 37568048, 2023). "FANCD2 patients often manifest a more severe phenotype and FANCD1/BRCA2 patients develop an early and rapidly lethal cancer-prone syndrome." (PMID 37627314, 2023). "At a cancer center in New York, researchers found 5 of the 22 patients (22.7%) with GBC had a pathogenic germline variant, 3 with BRCA2, and 1 each with an APC and NBN variants." (PMID 38163482, 2023). "Our findings expand on prior work where the frequency of non-BRCA1/BRCA2 PVs for women with MPCs (BC and another cancer diagnosis, including a second BC diagnosis) was 8.5% (47/551) among those followed in a high-risk BC program." (PMID 36856935, 2023). "In fact, two Pol θ inhibitors have been recently reported for the treatment of BRCA1 and BRCA2 related cancers." (PMID 36583344, 2023). "Induction of immune-associated responses, including the genes we identified, have been reported in biallelic BRCA2-mutant cancer cells." (PMID 37626143, 2023). "The BRCA1 and BRCA2 genes are significant players within the HR pathway, with the impaired function of these genes being the most studied cancer cellular mechanism relating to HRD." (PMID 37808268, 2023). "Since the discovery of the BRCA1 and BRCA2 genes in 1994 and 1995, the homologous recombination (HR) repair pathway for DNA damage has become a focus area for tumorigenesis and cancer therapy." (PMID 38098088, 2023). "Examples include PARP inhibitors such as olaparib, which have been shown to be effective in treating cancers with BRCA1 and BRCA2 mutations among others." (PMID 38163482, 2023). "Despite their close functional connection, BRCA1 and BRCA2 have somewhat different effects on cancer development and progression." (PMID 36902416, 2023).
cancer (continued). "A total of 99 (63.5%) females were unaffected and underwent genetic testing because of a known familial BRCA1 or BRCA2 PV, whereas 57 (36.5%) had a cancer diagnosis; 51 (32.7%) had BC and 8 (5.1%) had OC." (PMID 37887578, 2023). "The most frequent cancer sites in female relatives of BRCA2 carriers were the breast (32.2%), lung (3.7%), and ovary (2.4%), followed by the cervix and pancreas (1.5% each)." (PMID 36861435, 2023). "To date, Breast Cancer gene-2 (BRCA2) has the highest number of VUSs, which has necessitated the development of several robust functional assays to determine their functional significance." (PMID 37713444, 2023). "A small sample retrospective study showed that the frequency of BRCA2 mutations was 12.5% (2/16) in AVC patients, and the relatives of two patients had a history of cancer." (PMID 37274233, 2023). "The BRCA1 (OMIM # 113705) and BRCA2 (OMIM# 612555) genes are the most common and exhaustively studied, with a lifetime risk of developing cancer for BRCA mutation carriers of 60–80% for breast and 20–40% for ovarian cancers." (PMID 37444530, 2023). "Somatic mutations were recorded in 19% of localized PCs and 23% of mCRPC cancers, with the highest incidence in the BRCA2 and ATM genes." (PMID 36793600, 2023). "Given the high incidence of BC and the relatively low frequency of PVs in BRCA1 or BRCA2 in these carcinomas, there is a clear demand for a sensitive method to enrich for HRD tumors in a fast and cost-effective manner." (PMID 37725154, 2023). "Among BTC patients with both P/LP germline alterations and positive family cancer history, BRCA2 (20%, 4/20) was the most prevalent." (PMID 36072793, 2022). "This study investigates the associations between the risks of 22 cancers and BRCA1/2 PVs using data from 5,341 families segregating BRCA1 or BRCA2 PVs." (PMID 35077220, 2022). "Meta-analyses investigating the presence of BRCA genes in patients with cancer found that the missense variant was the most frequent in patients with BRCA1 and BRCA2 variants." (PMID 35251954, 2022). "Testing of patients with cancer for high penetrance breast-ovarian cancer susceptibility gene (CSGs) BRCA1, BRCA2 and PALB2 offers three potential benefits." (PMID 35868849, 2022). "Recent studies have found that the FEN1-specific inhibitor Compound #8 is abnormally sensitive to cancers with BRCA1 and BRCA2 deficiencies." (PMID 35883563, 2022). "Cancers with BRCA1 and BRCA2 mutations have homologous recombination deficiency resulting in error‐prone repair of double‐strand DNA breaks and overall genetic instability." (PMID 35128817, 2022). "Pathogenic variants in BRCA2/FANCD1, PALB2/FANCN, BRIP1/FANCJ, and RAD51C/FANCO have known adult-onset cancer risks, and there are recommendations for carriers to have increased cancer surveillance, consider chemoprevention, or undergo preventative surgeries." (PMID 35359366, 2022). "The SBS3 HR deficient signature has previously been associated with HRD and germline and somatic BRCA1 and BRCA2 mutations and BRCA1 promoter methylation in breast, pancreatic and ovarian cancers." (PMID 35637530, 2022). "Although there are indeed heritable mutations/genetic alterations that predispose to cancer and are therefore found in every cell that contains DNA (e.g., germline mutations in genes such as BRCA1 and BRCA2), these represent a minority of all cancer cases." (PMID 35703177, 2022). "Female carriers of germline pathogenic/likely pathogenic variants (P/LPVs) in the BRCA1/BRCA2 (BRCA) genes are at a substantially increased lifetime risk for developing breast, ovarian, and (to a lesser extent) other cancer types." (PMID 36230512, 2022). "For each patient, we also showed the risk in the well-known high-penetrance cancer risk alleles BRCA1 and BRCA2 with respect to other moderate-penetrance alleles including PALB2, CHEK2, ATM, BARD1, RAD51D, RAD51C and BRIP1." (PMID 35886069, 2022).
cancer (continued). "BRCAness defines the pathogenesis and treatment sensitivity of many types of cancer, as well as the presence of a defect in the homologous recombination repair of tumor cells simulating the loss of BRCA1 or BRCA2, as in the presence of germline mutations." (PMID 36613648, 2022). "The cancer-prone diseases, like those associated with BRCA1/BRCA2 mutations, are systematically associated with hyper-recombination." (PMID 35301607, 2022). "Our results underscore the importance of correctly classifying BRCA2 VUS as pathogenic variants can impact both future cancer risk and guide therapy selection during cancer treatment." (PMID 36098506, 2022). "Females harboring germline BRCA1/BRCA2 (BRCA) P/LPV are offered a tight surveillance scheme from the age of 25–30 years, aimed at early detection of specific cancer types, in addition to risk-reducing strategies." (PMID 36230512, 2022). "This large-scale registry-based case-control study analyzed BRCA1 and BRCA2 in 63 828 patients with 14 cancer types and 37 086 controls." (PMID 35420638, 2022). "High cancer risks, as applicable to BRCA1 and BRCA2 pathogenic variant (PV) carriers, can induce significant cancer concerns." (PMID 34997316, 2022). "The use of olaparib in cancer therapy is mainly based on its specific action in cells with BRCA1 and BRCA2 gene mutations." (PMID 35740913, 2022). "Recently, data on the differences in cancer risk association in male patients with BRCA1 and BRCA2 pathogenetic variants have emerged." (PMID 35454911, 2022). "By using promoter methylation level in BRCA2 as the cutoff, 16 of the 40 BRCAness gene promoters were hypermethylated across nearly all cancer types." (PMID 36497135, 2022). "For example, BRCA2 levels in human cancer cells rapidly diminish during HT, resulting in impaired repair of double-strand DNA breaks." (PMID 35625581, 2022). "The best-known genetic mutations associated with this cancer include mutations in the BRCA1 and BRCA2 genes." (PMID 35626173, 2022). "Unfortunately, due to the small number of BRCA2 gPV carriers with a DNA test before cancer diagnosis, we were unable to draw meaningful conclusions from the prospective analyses among BRCA2 gPV carriers and matched sporadic patients." (PMID 36137114, 2022). "BRCA1-type cancers typically display small (<10 kb) tandem duplications, in contrast to BRCA2-type cancers." (PMID 35159019, 2022). "Polygenic risk scores (PRS) that combine the effects of multiple disease-associated single nucleotide polymorphisms (SNPs) provide marked cancer risk stratification in the general population and BRCA1 and BRCA2 carriers." (PMID 34320204, 2022). "The results suggest that the range of cancer types associated with pathogenic variants in BRCA1 and BRCA2 is likely broader than that determined from previous analysis of largely European ancestry cohorts." (PMID 35420638, 2022). "Among these factors, mutations in tumor suppression genes breast cancer type 1 (BRCA1) and BRCA2 significantly increase the risk of OC, and these cancers can be prevented by chemoprevention and bilateral ovarian resection." (PMID 35335940, 2022). "Consistent with the low number of average mutations per sample, we find that the EGFR-mut cancers conserved 16 genes related to DNA repair (e.g., BRCA1 and BRCA2)." (PMID 36612014, 2022). "PV were detected in 13 cancer predisposition genes including ATM (n=4), BLM (n=1), BRCA1 (n=1), BRCA2 (n=7), BRIP1 (n=1), CDKN2A (n=1), CHEK2 (n=9), FANCC (n=1), MUTYH (n=10), NBN (n=1), PALB2 (n=1), RAD51D (n=1) and STK11 (n=1)." (PMID 36091166, 2022). "In a large cohort of the Chinese cancer population, the frequency of reversion mutations in pan-cancer unselected patients was 1.7%, with the most events reported in BRCA1, BRCA2, and PALB2 genes." (PMID 36557020, 2022).
cancer (continued). "C3 and C5, the dividing cancer cells, expressed BRCA1 and BRCA2, whose variant and insufficiency lead to HRD." (PMID 35892844, 2022). "Out of the total 7,919 samples containing 4,278 cancer patients and 3,641 cancer-free individuals, 729 were detected with BRCA1/2 deleterious germline mutations, of which 539 individuals carried BRCA1 mutations and 213 carried BRCA2 mutations." (PMID 35378767, 2022). "This information can potentially improve genetic testing of BRCA1 and BRCA2 for various cancer types for Asian countries and encourage similar research in other countries." (PMID 35420638, 2022). "Patients with biallelic PVs in FANCD1/BRCA2 or FANCN/PALB2 should have cancer surveillance at very young age, particularly focused on the associated cancers." (PMID 36091172, 2022). "A population-based study conducted in 32,247 women with BC screened for a panel of cancer predisposing genes found the majority of variants to occur in BRCA1 and BRCA2 genes." (PMID 36003761, 2022). "Upregulation of Pgp expression is considered a mechanism of resistance in BRCA1 and BRCA2 mutant cancers treated with PARPIs." (PMID 35785170, 2022). "Of the patients, 73.2% underwent genetic testing, and 30% of them presented germline likely pathogenic or pathogenic variants in cancer predisposition genes (24 BRCA1, 4 BRCA2, 1 PALB2, 1 NBN, and 1 ATM)." (PMID 36531080, 2022). "The results are the following distribution of cancer-associated mutations in genes: BRCA1 (31.4%), BRCA2 (12.2%), CHEK2 (10.5%) and other HCPS genes (45.9%), which is similar to our data." (PMID 36290365, 2022). "Cancer susceptibility in BRCA1 and BRCA2 mutation carriers has generally been attributed to increased chromosomal instability in BRCA1/2 deficient cells." (PMID 35017534, 2022). "They found that PEO1 BRCA2-mutant patient-derived cancer cells are unable to restrain fork progression in the presence of a low dose of HU." (PMID 36568963, 2022). "Intensive investigations into the mechanisms through which BRCA2 together with BRCA1 work as cancer suppressors have shown their key role as chromosome custodians with distinct functions which ensure the error-free resolution of DNA damage through HR repair." (PMID 35734584, 2022). "In this report we did a pan-cancer analysis using data reported on the Catalogue of Somatic Mutations in Cancers (COSMIC) to identify double mutants between RAD52 and BRCA1, BRCA2 or PALB2 that occur in cancer cells." (PMID 36107942, 2022). "Mutations in the genes involved in the breast cancer susceptibility gene (BRCA) signaling pathway, namely BRCA1, BRCA2, and PALB2, have been found in a subset of PDAC." (PMID 36556296, 2022). "The FDA has approved a number of mutations for cancer screening or cancer assaying, including mutations in the BRCA1 and BRCA2 genes for ovarian cancer, ALK rearrangements for NSCLC, and alterations in the PIK3CA gene for breast cancer patients." (PMID 35053452, 2022). "In total, 17 (94%) of the variants were private to a single person and were mostly related to cancer predisposition genes such as MUTYH, MSH6, BRCA2, and PALB2." (PMID 35562925, 2022). "It is reported that alteration of some DDR genes in cancers, including BRCA1, BRCA2, RAD51B, and RAD51C, is associated with therapy sensitivity." (PMID 36081518, 2022). "Hereditary breast and ovarian cancer (HBOC) can be caused by alterations in several genes, among which the tumour suppressors Breast cancer susceptibility gene 1 and 2 (BRCA1 and BRCA2) are the most prevalent and studied." (PMID 34981296, 2022).